MTOR (mechanistic target of rapamycin kinase)
Diseases named in the same sentence as MTOR in open-access papers (continued):
Sharing a sentence is not in itself a finding about the gene and the disease.
breast cancer (continued). "Indeed, in all breast cancer cell lines, both drugs determined the inhibition of phospho-mTOR protein expression, paralleled to a significant induction of autophagy, as shown by western blot analysis and quantification of the LC3-I conversion to the lipidated, autophagosome-associated form, LC3-II." (PMID 35761360, 2022). "Therefore, miR-760 could mediate autophagy and PI3K-AKT- mTOR pathway by targeting HM13 in breast cancer." (PMID 36153332, 2022). "Based on advances in the understanding of muscle-cancer cross talk, we hypothesized that pharmacologically active signaling factors released from contracting skeletal muscle would suppress anabolism in cultured MCF7 breast cancer cells by acting on the anabolic mTOR axis." (PMID 36388131, 2022). "In addition, the results showed that TUBB might mediate the development of metastasis in ERα-positive breast cancer patients possibly through the TSC/mTOR pathway." (PMID 36140469, 2022). "Also, inhibiting mTOR can restore the resistance of breast cancer cells to tamoxifen." (PMID 35558559, 2022). "Finally, this study suggests that a combination of polyamine biosynthetic inhibitor and mTOR pathway inhibitors might induced greater therapeutic benefit in some breast cancers." (PMID 36135836, 2022). "Finally, dual inhibition of polyamine and mTOR pathways may provide therapeutic benefits in some breast cancers." (PMID 36135836, 2022). "MIR200CHG can stimulate proliferation, invasion, and drug resistance in breast cancer by interacting with and normalizing YB-1, which is involved in regulating hypoxia-dependent gene transcription, and the hypo-phosphorylation of lactate metabolism related-signaling such as mTOR and HIF1 in cancer." (PMID 35422758, 2022). "Besides, CTet was found to activate the ER stress response, as well as upregulate recombinant DNA damage-inducible transcript 3 (DDIT3)/C/EBP homologous protein (CHOP) and DDIT4, subsequently inhibiting mTOR expression, leading to the induction of autophagy in breast cancer cells." (PMID 36104717, 2022). "Indeed, this principle has been demonstrated in breast cancer in a recent study that used an EGFR/HER2/VEGFR multi-RTK inhibitor (AEE788) in combination with mTOR rapalogs (rapamycin, temsirolimus, or everolimus) to re-sensitize triple-negative breast cancer cells to mTOR-targeted inhibition." (PMID 35326708, 2022). "Despite the high efficacy of everolimus for treating HR-positive advanced breast cancer, it can result in serious adverse effects, including interstitial pneumonia, infections, stomatitis, delayed wound healing, and hyperglycemia, because mTOR inhibition suppresses basic cellular processes." (PMID 35089453, 2022). "Also, this may serve as potential therapeutic angle needed to be explored for treatment of breast cancer with upregulated polyamine and mTOR pathways." (PMID 36135836, 2022). "Finally, we concluded that the synergistic combination provided a promising anti-neoplastic effect via reducing the angiogenesis, oxidative stress, increasing apoptosis,as well as inhibiting the activation of PI3K/AKT/mTOR cue, and suggesting its use as a treatment option for breast cancer." (PMID 35798765, 2022). "Notably, abnormalities in the PI3K–Akt–mTOR pathway also play a critical role in the development of breast cancer drug resistance, suggesting that this pathway is a highly promising candidate in breast cancer therapy." (PMID 36408240, 2022). "Moreover, a recent paper reported that HIF-2α could promote the apoptosis of breast cancer cells via PI3K/AKT/mTOR signaling pathway." (PMID 35486636, 2022). "Phase I/II clinical trials are currently underway to investigate dual‐PI3K/mTOR inhibitors in combination with chemotherapy or targeted therapies in breast cancer, renal cell carcinoma and prostate cancers and have promising results that may be useful for ovarian cancer trials in the future." (PMID 36114703, 2022).
breast cancer (continued). "This signalling pathway leading through AMPK activation to mTOR inhibition is thought to be, at least partly, responsible for both suppression of the proliferation and inhibition of the cell cycle in G1 phase as well as induction of apoptosis in breast cancer cells." (PMID 36497303, 2022). "In addition, it was found that miR-660-5p could promote breast cancer cell proliferation through the PI3K/AKT/mTOR pathway." (PMID 35883139, 2022). "In conclusion, our results demonstrate that the inhibition of endogenous H2S production can significantly inhibit the growth of human breast cancer cells via the AKT/PI3K/mTOR pathway and suggest that endogenous H2S may act as a promising therapeutic target in human BC cells." (PMID 35807290, 2022). "Thus, we first asked if MAL3-101 sensitive and resistant breast cancer cells exhibited unique sensitivities to the mTOR inhibitor, everolimus (also known as Afinitor), an FDA-approved rapamycin derivative that directly inhibits mTORC1 and indirectly inhibits mTORC2." (PMID 34180400, 2021). "The incidence of PIK3CA mutations, the activation of PI3K/Akt/mTOR signaling axis, and, in correlation with these, the increased mTORC2 activity (p-Ser473-Akt)–related HER2 expression were found to be involved in the liver metastases of breast cancers, which are occurring more frequently." (PMID 35029792, 2021). "In addition, there is growing evidence that combining mTOR inhibitors with chemotherapeutic agents (e.g., cisplatin, etc.)could have additional benefits, especially in breast cancers, which are principal models in our experiments." (PMID 34360785, 2021). "Intriguingly, mTOR inhibitors, such as temsirolimus and everolimus, have been proven to have secondary effects on angiogenesis in metaplastic breast cancer, suggesting that combining bevacizumab and temsirolimus/everolimus might be worthwhile for clinical trials." (PMID 33435254, 2021). "Furthermore, with regard to pathway activation status itself, the PI3K/AKT/mTOR pathway is known to be significantly more upregulated in TNBC as compared to other receptor subtypes of breast cancer, and is known to contribute to both hormonal therapy resistance as well as chemotherapy resistance." (PMID 34540690, 2021). "Considering the common alterations in AKT signaling molecules found in breast cancers and as their use as targets of anticancer drugs, the AKT/mTOR pathway was further investigated to determine whether it was involved in the inhibition of breast cancer progression by COL17." (PMID 34293053, 2021). "Besides, UCA1 also promotes breast cancer cells to resist tamoxifen by activating AKT/mTOR axis." (PMID 33565716, 2021). "Hence, cholesterol oleate may accelerate breast cancer proliferation via the AKT/mTOR pathway and inhibition of CE synthesis by avasimibe can lead to G0/G1 cell cycle arrest." (PMID 34201030, 2021). "Moreover, in breast cancer, as in other types of cancer, the suppression of mTOR and GAS5 may be mutual." (PMID 34202777, 2021). "Therefore, these preclinical data suggest that the combination of PI3K/AKT/mTOR inhibitors may be effective in overcoming resistance to immune checkpoint blockade therapy in breast cancer." (PMID 33790792, 2021). "Therefore, we examined whether GABARAP inhibited the EMT of breast cancer via regulation of the AKT/mTOR pathway." (PMID 33591943, 2021). "Indeed, a significant decrease in mTOR phosphorylation could be established for Ctsl−/− breast cancer cells." (PMID 32707827, 2020). "Finally, we studied whether differences in RAS/MAPK or AKT/mTOR signaling correlate with the increased metastatic potential of p66ShcA-expressing breast cancers." (PMID 31941526, 2020).
breast cancer (continued). "As loss of FAK-induced apoptosis in the mammary tumors of cKO-Wnt1 and cKD-Wnt1 mice and FAK deletion in Wnt tumor cells in vitro resulted in reduction of the mTOR signaling pathway, we wanted to explore whether mTOR pathway is responsible for apoptosis of the Wnt tumor cells." (PMID 32493400, 2020). "A recent study of kinome profiling of breast cancer cell lines using unbiased multiplexed inhibitor beads (MIBs), mass spectrometry (MS) demonstrated that resistance to drugs that target PI3K components, including AKT and mTOR, was associated with a failure to inhibit AURKA." (PMID 33371187, 2020). "Thus, utilizing an agent that will inhibit the expression of the mTOR protein, in addition to the inhibition of mTOR activation, may potentially improve the efficacy of breast cancer treatments and decrease drug resistance." (PMID 32012648, 2020). "Indeed, we found that mTOR inhibitor PP242 targeting both mTORC1 and mTORC2 could induce apoptosis in Wnt1-driven mammary tumor cells, supporting a role for mTOR to at least partially mediate FAK regulation of tumor growth and metastasis." (PMID 32493400, 2020). "We also demonstrated that combination therapy with a HER2 inhibitor and a AKT inhibitor, as well as other PI3K/AKT/mTOR pathway inhibitors, could overcome the therapeutic limitations associated with anti-HER2 monotherapy in the PIK3CA-mutant HER2+ breast cancers." (PMID 33303839, 2020). "Inhibition PAK1 could block the Akt/mTOR signaling pathway to benefit breast cancer therapy." (PMID 32863957, 2020). "As mounting evidence indicates that the mTOR pathway is associated with the development radio-resistance in tumours, as an indicator of mTOR activity p-S6K1 might be related with the development of radio-resistance in breast cancer." (PMID 31959810, 2020). "Aberrations in the phosphatidylinositol 3-kinase (PI3K)/Akt/mammalian target of rapamycin (mTOR) signaling pathway is a common mechanism of ET resistance, and inhibition of this pathway has also improved outcomes among patients with progressive ER+ breast cancer." (PMID 33144920, 2020). "After the withdrawal of rapamycin treatment, mutated COL1A1 reinforced PI3K–AKT-mammalian target of rapamycin (mTOR) signals in cancer stem cells to sustain the metastatic burden of ERα-positive breast cancer cells; however, lung metastases were independent of mTOR signaling." (PMID 31521169, 2019). "Data generated from this study suggests that inhibitors of the PI3K/AKT/mTOR pathway may be a viable strategy for many breast cancer patients, considering 59% of IDCs had measurable levels of PIK3CA mutation, and 26% of IDCs had levels of PIK3CA mutation ≥ 1 × 10−3." (PMID 30813596, 2019). "Off‐label use of everolimus might not provide sufficient benefit for refractory breast cancer patients harboring PI3K/AKT/mTOR pathway mutations." (PMID 31385461, 2019). "We predicted that DEPDC1 could activate the signaling of PI3K/AKT/mTOR in breast cancer cells." (PMID 31032225, 2019). "Moreover, targeting GLS and mTOR in advanced breast cancer may be a novel therapeutic approach in advanced ER+ breast cancer." (PMID 31428575, 2019). "They used a combination of therapy with a CDK inhibitor (roscovitine) plus a b-Raf-targeting pan-kinase inhibitor (sorafenib) or an mTOR inhibitor (rapamycin) to arrest the G1/S cell cycle in breast cancer cells; thus, the b-Raf-ERK1/2-mTOR signaling pathway could be suppressed." (PMID 31921802, 2019). "As PI3K and mTOR signaling are crucial regulators of radiation resistance and self-renewal in many carcinomas, including cervical carcinoma, head and neck squamous cell carcinoma, and breast carcinoma, it is important to note that mEAK-7 is also a strong effector of these processes." (PMID 31288154, 2019).
breast cancer (continued). "Activation of the PI3K-Akt-mTOR pathway may trigger endocrine resistance to tamoxifen and fluvestrant in breast cancer, while miR-214 could increase the sensitivity of breast cancer cells to 4-OHT/FUL through inhibition of autophagy via the PI3K-Akt-mTOR pathway." (PMID 30266744, 2018). "Rapamycin and its analogs temsirolimus, everolimus, and deforolimus, inhibitors of mTOR, are undergoing clinical evaluation for treatment of a variety of cancers, including breast cancer, supporting our notion that Src-AKT-STAT3 signaling may be crucial for chemoresistance in TNBC cells." (PMID 30473665, 2018). "Additionally, in vitro tamoxifen treatment of breast cancer stem cells resulted in endocrine resistance that could be reversed with an mTOR inhibitor." (PMID 29128895, 2018). "It is thought that MET in culture conditions with high concentrations of glucose stimulates AMPK through an LKB1-dependent mechanism, which blocks mTOR, causing a powerful inhibition of cell proliferation in several types of cancer cells specially non-TN breast cancer cells." (PMID 30483391, 2018). "In addition, we confirmed that PTPN13 is a SMYD2 transcriptional target gene in TNBC cells, which may link SMYD2 to other breast cancer associated signaling pathways, including ERK, mTOR, and Akt signaling." (PMID 29487338, 2018). "Our research study aims were to investigate whether apoptosis of human breast cancer MCF-7 cells could be induced by 20(S)-PPD by targeting the Phosphatidylinositol 3-kinase/Protein kinase B/Mammalian target of rapamycin (PI3K/AKT/mTOR) signal pathway in vitro and in vivo." (PMID 29614812, 2018). "However, it is uncertain whether AM extract induces breast cancer cells apoptosis only through the PI3K/Akt/mTOR signaling pathway or by other pathways." (PMID 29523109, 2018). "Recently, biological studies have shown that PI3K/AKT/mTOR signaling pathway, which is closely related to the activation of cancer cell growth, survival, and migration and drug resistance of targeted therapy, is abnormally activated in many cancers, including breast cancer." (PMID 29614812, 2018). "The PI3K/AKT/mTOR pathway plays an important role in proliferation, differentiation and survival of cells and has been shown to be associated with resistance to endocrine therapy, human epidermal growth factor receptor 2 (HER2)-directed therapy and cytotoxic therapy in breast cancer." (PMID 29983888, 2018). "To test whether targeting mTOR and DNA repair could be a relevant therapeutic strategy in triple-negative breast cancer, we tested the combination of everolimus and olaparib in PDX model established from a BRCA2-mutated basal-like breast cancer." (PMID 30038706, 2018). "Hence, anti-estrogens may suppress ER+ breast cancer growth in part by decreasing PI3K/AKT/mTOR signaling." (PMID 29507656, 2018). "Thus, we make a hypothesis that the human breast cancer MCF-7 cell apoptosis induced by 20(S)-PPD may be related to targeting of the PI3K/AKT/mTOR signal pathway." (PMID 29614812, 2018). "The mTOR inhibitors everolimus and temsirolimus have already been approved for the treatment of metastatic renal cell carcinoma (temsirolimus, everolimus), mantle cell lymphoma (temsirolimus), breast cancer (everolimus), and pancreatic neuroendocrine tumors (everolimus)." (PMID 30200497, 2018). "Indeed, as a mTOR inhibitor, everolimus exerts its action on a target placed within a particularly complex network of pathways involved in the regulation of both the metabolic profile of the host and breast cancer development and progression." (PMID 28878375, 2017). "Notably, activation of mTOR signaling is closely related to endocrine resistance in breast cancer." (PMID 28793923, 2017). "Moreover, the effects of metformin on glucose metabolism and mTOR signaling inhibition are also implicated in cancer stem cell (CSC) regulation as previously shown in syngeneic tumor, xenograft tumor, and transgenic mouse models of breast cancer." (PMID 28193239, 2017).
breast cancer (continued). "Targeting mTOR signalling combined with endocrine therapy may improve breast cancer treatment." (PMID 28272775, 2017). "However, the role of mTOR expression in the prognosis of breast cancer remains controversial." (PMID 28114374, 2017). "Thus, whether or how CPT should reverse the resistance via inhibiting ACSL4‐mediated mTOR in breast cancer needs to be elucidated in the future work." (PMID 28272775, 2017). "However, increasing amounts of evidence have indicated that multiple factors also contribute to breast cancer development, such as estrogen level, estrogen receptor status, inflammation, macrophage activity, DNA repair ability, and overactivation of mTOR survival signaling." (PMID 29109519, 2017). "In addition, downregulation of GAS5 has been associated with chemoresistance in some malignant neoplasms, by affecting the sensitivity to adriamycin in gastric cancer, trastuzumab in breast cancer, mTOR inhibition in prostate cancer, and EGFR tyrosine kinase inhibition in wide-type EGFR NSCLC." (PMID 29029523, 2017). "Therefore, it is possible that the PI3K/Akt/mTOR pathway might be involved in the TRIM44-dependent NF-κB activation in breast cancer cells." (PMID 28885545, 2017). "Therefore, the PI3K/AKT/mTOR pathway plays a key role in the development of breast carcinoma." (PMID 28114374, 2017). "This could be due to the fact that mTOR is highly expressed in breast cancer cell lines." (PMID 26840281, 2016). "Employing MTI-31 and earlier mTOR-KIs, we further demonstrated that the profound antitumor efficacy of the mTOR-KIs is dependent on cancer driver mutation status of the tumors and involves molecular regulation of apoptotic machinery and lipid metabolism in HER2+/PIK3CAmut breast cancer." (PMID 27563814, 2016). "Our finding of defective proteolysis of mTOR protein could be potentially exploited for improving the efficacy of breast cancer treatment regimens and mitigating drug resistance as well as providing a basis for potential novel therapeutic modalities for breast cancer." (PMID 27748082, 2016). "Moreover, our data demonstrate that APA inhibits Akt/mTOR and P70 S6k in breast cancer cells." (PMID 26943775, 2016). "Finally, the use of a pan-inhibitor of Aurora kinases, danusertib, promoted cellular apoptosis and autophagy, and inhibited the EMT in breast cancer cells, via modulation of p38 MAPK/Erk 1/2/Akt/mTOR signaling pathways, making this a promising anticancer treatment for breast cancer." (PMID 27429011, 2016). "Thus, more recent trials are evaluating mTOR inhibition with everolimus in the adjuvant setting in high-risk estrogen receptor-positive, HER2-negative early breast cancer (BOLERO-2) or in trastuzumab resistant, HER-2 positive, advanced breast cancer patients (BOLERO-3)." (PMID 27155197, 2016). "Therefore, targeting ECM/integrin β1/mTOR pathway may be a promising therapeutic strategy to overcome chemotherapy resistance in breast cancer." (PMID 27487140, 2016). "However, in the recently completed BOLERO-3 randomized phase-III study of Trastuzumab-resistant advanced breast cancer, the addition of the mTOR-inhibitor Everolimus to Trastuzumab and Vinorelbine treatment showed some clinical benefit only in hormone receptor negative (HR−) patients." (PMID 27876799, 2016). "Therefore, high mTOR protein could be potentially involved in promoting the cancerous phenotype of breast cancer cells." (PMID 27748082, 2016). "Activation of the PI3K/Akt/mTOR signaling pathway in breast cancer could be as frequent as 70%." (PMID 26599012, 2015). "Interestingly, when patients learned about the benefits and risks of the treatment options that they had—aromatase inhibitor vs aromatase inhibitor plus mTOR inhibitor—for this type of breast cancer after failure of standard treatments, they tended to agree what attributes were important to them." (PMID 26558177, 2015).